KDM3A (lysine demethylase 3A)
Diseases named in the same sentence as KDM3A in open-access papers (continued):
Sharing a sentence is not in itself a finding about the gene and the disease.
renal cell carcinoma (2 papers, 2011 to 2020). "Emerging evidence has found that histone demethylases (KDMs), the key regulators in histone modifications, such as KDM3A, KDM5C, KDM6A, and KDM6B, can promote renal cell carcinoma (RCC) progression via hypoxia-mediated angiogenesis pathways." (PMID 32092824, 2020).
atherosclerosis (1 paper, 2022). A disease characterized by the build-up of fatty material and calcium deposition in the arterial wall resulting in partial or complete occlusion of the arterial lumen. "Other than that, KDM3A has been identified as important regulator of neointima formation in experimental atherosclerosis whilst KDM4A mediates oxidized LDL-induced pro-inflammatory Mac polarization." (PMID 36552592, 2022).
autism (1 paper, 2016). Persistent deficits in social interaction and communication and interaction as well as a markedly restricted repertoire of activity and interest as well as repetitive patterns of behavior. "The LoF variants in this gene and several members of the same family (KDM3A, KDM5B, KDM6B) have recently been associated with autism in a large scale genetic investigation." (PMID 27257017, 2016).
brain cancer (1 paper, 2019). A primary or metastatic malignant neoplasm affecting the brain. "KDM6A was significant in pediatric brain cancer and marginally significant in adenocarcinomas of the lung and stomach while KDM3A was marginally significant in stomach adenocarcinoma." (PMID 31294536, 2019).
breast ductal carcinoma (1 paper, 2016). "Integrated data from multiple gene-expression-profiling studies of breast ductal carcinoma (720 patients) and oral and skin SCC (47 patients) showed a significant positive correlation between JMJD1a (KDM3A) and TAZ (WWTR1) gene expression." (PMID 27488962, 2016).
chronic heart failure (1 paper, 2022). "Long noncoding RNA HOX transcript antisense RNA (HOTAIR) has been studied in multiple diseases, but the role of HOTAIR on chronic heart failure (CHF) through the regulation of microRNA (miR)‐30a‐5p and lysine‐specific demethylase 3A (KDM3A) remains unexplored." (PMID 35083842, 2022).
chronic kidney disease (1 paper, 2020). Impairment of the renal function secondary to chronic kidney damage persisting for three or more months. "Results from a previous study suggested that the expression of KDM3A was elevated in chronic kidney disease." (PMID 32092824, 2020).
diffuse large B-cell lymphoma (1 paper, 2016). "Interestingly, knockdown of KDM3A also significantly impaired growth of diffuse large B-cell lymphoma (DLBCL) cell lines." (PMID 26728187, 2016).
experimental autoimmune encephalomyelitis (1 paper, 2013). An autoimmune demyelinating disease of the central nervous system that is produced experimentally in animals by the injection of homogenized brain or spinal cord in Freund's adjuvant. "Both homozygous (Kdm3a−/−) and heterozygous (Kdm3a+/−) knockout mice were susceptible to experimental autoimmune encephalomyelitis and displayed equivalent incidence and severity of disease compared to wild type littermate controls." (PMID 24312603, 2013).
medulloblastoma (1 paper, 2015). A malignant, invasive embryonal neoplasm arising from the cerebellum. "In line with our previous data of KDM3A as a GLI-stimulating factor, we found Kdm3a mRNA expression to be increased in two independent mouse models of Hh-driven medulloblastoma." (PMID 26310823, 2015).
myeloid malignancies (1 paper, 2021). "In myeloid malignancies, KDM3A has been shown to demethylate H3K9me2, while KDM3B is associated with histone demethylase activity towards H3K9me1–2." (PMID 34944554, 2021). "To date, this is the only study describing a role for KDM3A in myeloid malignancies; further investigation is therefore required to corroborate the significance of KDM3A-mediated CDX2 overexpression in this context or to reveal additional pathophysiological roles for KDM3A." (PMID 34944554, 2021).
pancreatic adenocarcinoma (1 paper, 2022). "For example, KDM3A upregulates the CSC marker DCLK1 by binding to the DCLK1 promoter in pancreatic adenocarcinoma." (PMID 36008383, 2022).
triple-negative breast carcinoma (1 paper, 2024). An invasive breast carcinoma which is negative for expression of estrogen receptor (ER), progesterone receptor (PR), and human epidermal growth factor receptor 2 (HER2). "The purpose of this study was to investigate the effect of KDM3A expression with triple-negative breast cancer (TNBC) invasion and metastasis." (PMID 38165573, 2024).
tumor (78 papers, 2010 to 2026). "illustrated that knockdown of KDM3A inhibited the proliferation of tumor cells and was linked to drug resistance." (PMID 33816782, 2021). "Among them, KDM3A is especially known to promote cancer cell proliferation, survival, and migration as well as tumor metastasis; it is associated with poor prognosis in various cancer types." (PMID 32354028, 2020). "Uemura and colleagues established that KDM3A was an independent prognostic factor for CRC, and that KDM3A inhibition was associated with decreased proliferative activity and reduced invasion in CRC cell lines and tumor xenografts." (PMID 40699666, 2025). "BG scaffold with NS loaded surface coating.IOX1 suppresses KDM3A to boost tumor epigenetic sensitivity to PTT." (PMID 41255574, 2025). "The stimulation of IFN response by KDM3A knockout was associated with the increased expression of ERVs, and the reduction in tumor growth by KDM3A knockout was dependent on the modulation of type I IFN pathway." (PMID 40940894, 2025). "Specifically, the ablation of KDM3A enhances tumor‐intrinsic interferon levels through the ERV‐MAVS‐IFN axis, leading to a remodeled TME that effectively inhibits tumor growth." (PMID 39031630, 2024). "The results shows that KDM3A over‐expression suppresses the tumor‐intrinsic IFN response and inhibits KDM3A, either genomically or pharmacologically, which effectively promotes IFN responses by activating endogenous retroviruses (ERVs)." (PMID 39031630, 2024). "Lysine demethylase 3A (KDM3A) regulates anti-tumor immunity through epidermal growth factor receptor (EGFR) expression in cancer cells." (PMID 38817612, 2024). "Ack1-induced tumor resistance to anticancer agents is mediated through the interaction of Ack1 with the estrogen receptor (ER)/histone demethylase KDM3A (JHDM2a) complex." (PMID 39123481, 2024). "Collectively, these results affirm that KDM3A is a promising therapeutic target for suppressing tumor growth." (PMID 39031630, 2024). "Remarkably, KDM3A knockdown not only significantly inhibited tumor growth of MDA-MB-231 cells in vivo but also suppressed metastasis in nude mice, providing further support for the potential therapeutic targeting of KDM3A in TNBC." (PMID 38165573, 2024). "Among all of the members of the KDM3 family, the oncogenic function of KDM3A is most frequently reported in the literature, as it mediates cancer cell proliferation, survival, migration, and tumor metastasis." (PMID 39519018, 2024). "This indicates that KDM3A can exhibit both oncogenic and tumor suppressive properties, potentially depending on the specific cellular context and gene expression profiles regulated by KDM3A in different types of neoplasms." (PMID 38165573, 2024). "To validate the role of KDM3A in regulating tumor‐intrinsic IFN, we generated KDM3A knockout cell lines using CRISPR/Cas9 in both mouse (MFC) and human (AGS) cell lines." (PMID 39031630, 2024). "In parallel, an overall increase in H3K9me2 erasers (KDM3B and KDM4A in basalioma, and KDM3A in the other two tumor types) and a bladder-specific decrease in the reader PRDM6 involved in K9 dimethylation were found." (PMID 37569534, 2023). "It has been reported that KDM3A has a role in various biological processes, such as cell proliferation, migration, tumor cell infiltration, and angiogenesis." (PMID 36092165, 2022). "Studies on KDM3A have majorly focused on cancer, where it enhances tumor cell proliferation, migration, invasion, and angiogenesis." (PMID 36092165, 2022). "Taken together, these findings indicate that KDM3A is an important oncogene in ccRCC, and promotes tumor growth and metastasis while functioning as the main executor of miR-335." (PMID 33888871, 2022). "Silencing of KDM3A also reduced the tumor infiltration area in mouse lung areas when the HOS cells were injected via the tail vein." (PMID 35590288, 2022).
tumor (continued). "Analysis of the clinical expression data in the TCGA-LIHC cohort showed that both CEP131 and KDM3A were upregulated in tumour tissues compared to NT tissues." (PMID 36008383, 2022). "We have shown that the expression of Kdm3a, lysine-specific demethylase for histones, in 4T1.2 tumor cells was downregulated by Oct4 CM and c-Myc CM." (PMID 35547745, 2022). "In the present study, we validated that KDM3A was highly expressed in the OS tumor tissues and cells, and it was correlated with disease prognosis in patients." (PMID 35590288, 2022). "These newly identified tumor suppressors, such as extracellular Eno1, Hsp90ab1, Eef2, and vinculin, downregulated Kdm3a, a histone demethylase, as well as the downstream oncogenic genes 21-24." (PMID 35547745, 2022). "Recent studies have shown that KDM3A is a direct target of hypoxia-inducible transcription factors, acting as an oncogene to enhance tumour migration, invasion and stemness." (PMID 36008383, 2022). "KDM3A, also known as JMJD1A or JHDM2A, is of great significance for gene regulation in various biological activities, such as tumour progression." (PMID 34350711, 2021). "The results revealed that the KDM3A gene exhibited a more distinct change between tumor-free lung and NSCLC tissue specimens than did the PQLC2 gene, and KDM3A was upregulated in NSCLC (p < 0.05)." (PMID 33816782, 2021). "In a work published in 2020, an in vivo CRISPR screening, performed using mouse clonal congenic primary tumour cell lines, identified lysine demethylase 3A (KDM3A) as a potent epigenetic regulator of immunotherapy response in PC." (PMID 33671588, 2021). "To evaluate the role of KDM3A in tumor growth, we employed an orthotopic gastrocnemius injection model in NOD-SCID/Gamma mice." (PMID 32577157, 2020). "In particular, KDM3A and KDM6B are activated in hypoxic tumors and associated with tumor aggressiveness and progression." (PMID 33318475, 2020). "In a tumor xenograft mouse model, both the tumor growth and volume were diminished in KDM3A-depleted tumors." (PMID 32354028, 2020). "We further show that KDM3A depletion in FP-RMS cells inhibits both tumor growth and metastasis in vivo, and that RMS cells are highly sensitive to colony growth inhibition by the pan-JHDM inhibitor JIB-04." (PMID 32577157, 2020). "The qRT-PCR analysis determined downregulated miR-202-3p and upregulated KDM3A in HCC tissues when comparable to tumor-free liver tissues." (PMID 33520978, 2020). "The depletion of KDM3A by shRNA treatment suppresses the growth of HCC HepG2 tumor xenografts in vivo." (PMID 32354028, 2020). "KDM3A, induced by hypoxia and nutrient starvation within the tumor microenvironment, shows carcinogenic effects via the promotion of tumor cell migration and invasion." (PMID 31871779, 2019). "We have identified small molecule inhibitors of KDMs including JIB-04 that showed oral activity in tumor suppression and blocked KDM3A in vitro." (PMID 30531796, 2018). "In these tumors, Kdm3a is strikingly downregulated, resulting in a loss of its opposing role to the oncogenic H3K9 methyltransferase G9a and an increase in tumor growth." (PMID 29156681, 2017). "The results discussed so far clearly showed that KDM3A is crucial for tumor cell proliferation, apoptosis resistance and CSCs maintenance." (PMID 27694900, 2017). "Our data demonstrated that Kdm3a can directly upregulate cyclin D1 expression to promote mammary gland epithelial cell and tumor cell proliferation." (PMID 29156681, 2017). "In summary, this study revealed that Kdm3a can promote mammary gland epithelial and tumor cell proliferation to facilitate mammary gland ductal elongation and tumor growth through upregulating cyclin D1 expression." (PMID 29156681, 2017). "Recent studies have shown that Kdm3a plays an important role in self-renewal of embryonic stem cells, spermatogenesis, metabolism, sex determination and tumor angiogenesis." (PMID 29156681, 2017).
tumor (continued). "Our findings suggest that Kdm3a plays an important genetic role to promote mammary gland epithelial proliferation, ductal growth and tumor growth in vivo." (PMID 29156681, 2017). "In this study, we combine systematic and biochemistry approaches and prove that H3K9me2/3 decreases and KDM3A/JMJD1A increases in tumor cell transformation model and in vivo clinical samples." (PMID 27034728, 2016). "Vitamin D induced miR-627 expression to downregulate KDM3A and consequently inhibited xenograft tumor growth in nude mice, suggesting that targeting KDM3A may have the same anti-tumor activities as vitamin D." (PMID 40699666, 2025). "In ARMS, the depletion of KDM3A reduces colony formation, migration, invasion, and tumor growth." (PMID 40508013, 2025). "Leveraging advanced bioinformatics techniques, the identification of 12 crucial genes (ETNK1, BICRA, IL-1R1, KDM3A, ARID2, GSK3β, EZH2, NOTCH1, SMARCA4, FOS, CREB1, CASP3) associated with the tumor-suppressing miR-101-3p network stands out as a notable achievement." (PMID 40074445, 2025). "In vivo, KDM3A knockdown significantly inhibited tumor growth in xenograft models." (PMID 41183175, 2025). "Collectively, these findings indicate that KDM3A could be a potential therapeutic target for inducing tumor‐intrinsic IFN." (PMID 39031630, 2024). "Based on these analyses and the literature, we hypothesized that KDM3A plays a crucial role in regulating tumor‐intrinsic IFN and could be a potential target for modulating the TME." (PMID 39031630, 2024). "KDM3A ablation may activate ERVs expression, stimulating tumor‐intrinsic IFN response and remodeling the TME to enhance antitumor immunity." (PMID 39031630, 2024). "KDM3A plays an important role in tumorigenesis and development, Functioning as a crucial regulator of tumor growth and metastasis, KDM3A holds considerable promise as a potential target for anticancer therapies by impeding the activity of oncogenic transcription factors." (PMID 38165573, 2024). "Herein, we observed that KDM3A ablation in AGS cells significantly inhibited tumor cell viability." (PMID 39031630, 2024). "Furthermore, the antitumor effects of KDM3A ablation were weakened by anti‐IFNAR1 antibody treatment, suggesting that KDM3A ablation suppressed tumor growth and enhanced antitumor immunity in a type I IFN dependent manner." (PMID 39031630, 2024). "Additionally, KDM3A inhibition resulted in decreased tumor growth in a human tumor cell xenograft nude mouse model." (PMID 39031630, 2024). "KDM3A is overexpressed in ccRCC and may promote tumor growth and metastasis by activating yes-associated protein 1 (YAP1) expression through epigenetic mechanisms, thus establishing a miR-335/KDM3A/YAP1 regulation axis." (PMID 33888871, 2022). "Also, the tumor metastasis in lung tissues, which was suppressed by sh-KDM3A, was increased after SP1 upregulation in HOS cells." (PMID 35590288, 2022). "Notably, KDM3A has become relevant to tumour progression due to recent findings of this enzyme’s role in promoting cancerous phenotypes, such as enhanced glucose consumption and upregulated mechanisms of chemoresistance." (PMID 35625569, 2022). "Furthermore, expression of KDM3A, p21, cleaved caspase-3, and caspase-3 biochemically from tumor samples changed similarly as observed in H1299 cells." (PMID 33816782, 2021). "Moreover, KDM3A, a histone demethylase in the JmjC domain‐containing protein family, is known to be up‐regulated in tumours and exerts a pro‐tumorigenic function." (PMID 33350586, 2021). "Knockout of Kdm3a inhibits tumor formation in Pik3ca transgenic mouse livers." (PMID 32354028, 2020). "Furthermore, the downstream axis involving KDM3A/HOXA1/MEIS3 was proposed to be essential for miR-202-3p to facilitate its functionality as a tumor suppressor." (PMID 33520978, 2020).